CHD2 (chromodomain helicase DNA binding protein 2)
Diseases named in the same sentence as CHD2 in open-access papers (continued):
Sharing a sentence is not in itself a finding about the gene and the disease.
Epileptic encephalopathy (16 papers, 2014 to 2025). A condition in which epileptiform abnormalities are believed to contribute to the progressive disturbance in cerebral function. "Heterozygous CHD2 variants (MIM: 602119) have been identified in neurodevelopmental disorders characterized by early-onset epileptic encephalopathy and cognitive regression." (PMID 39035822, 2024). "CHD2 is required for neural circuit and its mutation is a driver of abnormal brain function, early onset epileptic encephalopathy and intellectual disability." (PMID 38225273, 2024). "CHD2 and CHD4 increase the risk of epileptic encephalopathies, and CHD2, along with CHD5 and CHD6, confer risk for ID." (PMID 31036712, 2019). "Photosensitivity is prominent in a very rare epileptic encephalopathy due to de novo CHD2 mutations, but is also seen in epileptic encephalopathies due to other gene mutations." (PMID 25783594, 2015). "Despite that, consanguinity in family 2 could account for the dissimilar phenotype severity compared with families 1 and 3, in addition to the CHD2 variant being identified by epileptic encephalopathy panel testing instead of ES." (PMID 39035822, 2024). "Then, we reviewed a total of 144 individuals carrying CHD2 variants with epileptic encephalopathy." (PMID 35222528, 2022). "New cases with novel variants, along with a detailed clinical and molecular analysis, are important for a better understanding of CHD2-related epileptic encephalopathy." (PMID 35627293, 2022). "Photosensitivity occurs in some epileptic encephalopathies, such as Dravet syndrome due to mutation in SCN1A and encephalopathy associated with mutation in CHD2." (PMID 25783594, 2015). "To date, there are 144 reported individuals encompassing 126 single-nucleotide or indel variants (non-CNVs) and 18 copy number variants (CNVs) with CHD2-related epileptic encephalopathy." (PMID 35222528, 2022). "However, it was noted that CHD2, a protein that belongs to the same family as CHD1L, has been strongly implicated in epileptic encephalopathy in several recent studies." (PMID 24885232, 2014). "Though a series of studies indicated that there was no clear correlation between genotypes and phenotype in CHD2-related epileptic encephalopathy, we thought that it was necessary to further research the association between genotypes and phenotypes." (PMID 35222528, 2022).
autism (9 papers, 2017 to 2026). Persistent deficits in social interaction and communication and interaction as well as a markedly restricted repertoire of activity and interest as well as repetitive patterns of behavior. "Likewise, many neuronal genes with H3K27ac gain and increased expression under CHD2 deficient conditions are linked to the etiology of autism and other NDDs, including MYT1L, NRXN3, SLC12A5, and SNAP25 32–35." (PMID 36115870, 2022). "Based on known risk genes for ASD36 and CHD2, autism risk genes are under stronger negative selection of loss of function variants (“s_het”37) than CHD risk genes." (PMID 33479230, 2021).
developmental and epileptic encephalopathy (8 papers, 2018 to 2026). An epilepsy associated with developmental impairment that may be due to either the underlying etiology or the superimposed epileptic activity, or both. "While mutations in most of the CHD proteins have been described and demonstrated to lead to a range of cancers and developmental diseases, a number of gene variants in the gene encoding CHD2 were identified as the cause of a developmental epileptic encephalopathy (CHD2-DEE)." (PMID 33435571, 2021). "CHD2 pathogenic variants cause a developmental and epileptic encephalopathy." (PMID 33944996, 2021). "In this review, we will discuss the role of the CHD family of chromatin remodeling proteins in neurodevelopmental disorders, focusing specifically on CHD2, which is associated with developmental and epileptic encephalopathy (DEE), a severe form of childhood epilepsy." (PMID 29962935, 2018). "The CHD2 gene is one of the most common causative genes of developmental and epileptic encephalopathy (DEE)." (PMID 41383239, 2025). "In the current review, we discuss how the canonical role of CHD2 may influence the variable phenotypic presentations of CHD2-developmental epileptic encephalopathy (CHD2-DEE), and the possibilities for future therapies to treat this complex disorder." (PMID 33435571, 2021).
developmental delay (8 papers, 2014 to 2024). "We investigated 17 patients from 17 unrelated families carrying monoallelic CHD2 variants who presented with childhood-onset myoclonic seizures, intellectual disability (ID), severe global developmental delay (GDD), and poor response to treatment." (PMID 39035822, 2024). "In this study, a girl with developmental delay and myoclonic epilepsy caused by a new mutation c.4318C>T (pArg1440*) in the CHD2 gene was studied using WES." (PMID 35222528, 2022). "This study reported a novel variant in the CHD2 gene in a Chinese girl with developmental delay and myoclonic epilepsy through whole-exome sequencing (WES)." (PMID 35222528, 2022). "Pathogenic variants in CHD2 have been reported to have a wide range of phenotypic variability in neurodevelopmental disorders, such as early-onset epileptic encephalopathy, developmental delay, and behavior problems." (PMID 35222528, 2022). "Two (4.7%; IDs 13 & 14) patients with seizure onset at 35 and 36 months who exhibited ataxia, developmental delay, feeding, and behavioral problems were found to have DEE-associated variants in CHD2." (PMID 34469436, 2021). "We present the clinical features of four individuals with heterozygous de novo deletions affecting CHD2 who were identified from among a phenotypically heterogeneous cohort of 42,313 patients with developmental delays or ID, multiple congenital anomalies and/or ASD." (PMID 24834135, 2014). "Interestingly, all the patients with CHD2 CNVs could lead to developmental delays in pre-seizure onsets, such as motor and speech developmental delays." (PMID 35222528, 2022). "Considering the patient’s seizures and developmental delay, and the fact that there are no other variants that could cause these phenotypes in the patient, we considered that the c.3783G>A variant of CHD2 was a likely pathogenic variant and was responsible for the patient’s phenotypes." (PMID 35627293, 2022). "Pathogenic variants in CHD2 have also been identified in cohorts of patients diagnosed with other neurodevelopmental disorders, including ASD, ID and developmental delay, some of whom did not present with seizures." (PMID 29962935, 2018).
Dravet syndrome (8 papers, 2018 to 2025). "Eight individuals (6.2%) had died after their last follow-up; four had SCN1A-related Dravet syndrome; the others had CHD2, GNAO1, KCNT1 and NEXMIF-related DEEs." (PMID 39882024, 2025). "A gene-based collapsing analysis highlighted an increased variant burden in CHD2, FLNA and TSC1 (P < 0.05) in Dravet syndrome compared with GEL SCN1A controls that was not significant after correction for multiple comparisons." (PMID 37006128, 2023).
Doose syndrome (7 papers, 2015 to 2024). "Although the functional studies of CHD2 are limited, it has been reported that pathogenic variants of CHD2 would lead to developmental and epileptic encephalopathy-94 (DEE94, OMIM 615369)." (PMID 35627293, 2022). "Another newly implicated gene, CHD2 (chromodomain helicase DNA-binding protein 2), had been described in childhood onset epileptic encephalopathy and myoclonic astatic epilepsy." (PMID 27598577, 2016). "Defects in Chromodomain Helicase DNA-Binding Protein 2 (CHD2) are known to cause developmental and epileptic encephalopathy 94 (MIM#615369), whereas Regulator of Nonsense-Mediated mRNA Decay (UPF3B) is associated with X-linked syndromic intellectual developmental disorder 14 (MIM#300676)." (PMID 37563452, 2024).
photosensitive epilepsy (6 papers, 2015 to 2024). An epilepsy characterized by seizures triggered by visual stimuli that form patterns in space or time, such as flashing lights. "We identified 11 unique variants in the 580 individuals with photosensitive epilepsies and 128 unique variants in the 34 427 controls: unique CHD2 variation is over-represented in cases overall (P = 2·17 × 10−5)." (PMID 25783594, 2015). "Investigators from multinational institutions hypothesized that disruption of CHD2, which encodes chromodomain helicase DNA-binding protein 2, would be associated with common forms of photosensitive epilepsy or photosensitivity manifesting as a photoparoxysmal response alone." (PMID 26933602, 2015). "CHD2's link to photosensitive epilepsy is acknowledged, but this study suggests that its impact extends beyond this condition alone." (PMID 39035822, 2024). "Additional studies investigating protein interacting partners and post-translational modifications of CHD2 will be necessary to understand how abnormal CHD2 leads to photosensitive epilepsy." (PMID 25783594, 2015). "Authors identify CHD2 as a photosensitive epilepsy gene and an important contributor to both the absence seizures with eyelid myoclonia seizure type and eyelid myoclonia with absences epilepsy syndrome." (PMID 26933602, 2015). "At present, the relationship between photosensitive epilepsy and other genes involved is not very clear, in spite of bromodomain-containing protein 2 and CHD2 being known as a likely susceptible gene in photosensitive epilepsy." (PMID 30534049, 2018). "The ExAC cohort is also the biggest relevant control data set available, and the most likely of any existing data set to provide an accurate estimate of the true frequency of unique variation in CHD2 in a population not enriched for photosensitive epilepsy." (PMID 25783594, 2015). "Since both stx1b and chd2 gene mutations can lead to MAE, whether or not STX1B is also related to photosensitivity epilepsy like CHD2 is, remains a question." (PMID 30534049, 2018).
breast carcinoma (4 papers, 2016 to 2025). "This is based on the crucial function of Chd2 in maintaining development, as Chd2 is a candidate gene target of breast cancer genetic susceptibility gene Mtsm1." (PMID 41278204, 2025). "CHD2 has been proposed to prevent breast cancer initiation, and CHD2 mutations are associated with chronic lymphocytic leukemia." (PMID 35467222, 2022).
childhood-onset epileptic encephalopathy (4 papers, 2016 to 2022). "Previously, CHD2 variants were generally considered to be childhood-onset epileptic encephalopathy." (PMID 35222528, 2022). "CHD2 (childhood-onset epileptic encephalopathy) is recruited by PARP1 to sites of DNA damage in HEK293 and U2OS cells." (PMID 32737294, 2020).
Encephalopathy (4 papers, 2015 to 2024). Encephalopathy is a term that means brain disease, damage, or malfunction. "These possible additional intricacies in the gene regulation interactions that govern CHD2 expression and function may account to some extent for the variable phenotypes seen in CHD2 encephalopathies." (PMID 33435571, 2021).
epilepsy syndrome (4 papers, 2015 to 2025). A syndrome that has a characteristic cluster of clinical features and/or lectroencephalographic (EEG) findings that reflect underlying epileptic activity. "Among epilepsy syndromes, there was over-representation of unique CHD2 variants (3/36 cases) in the archetypal photosensitive epilepsy syndrome, eyelid myoclonia with absences (P = 3·50 × 10−4)." (PMID 25783594, 2015). "Finally, three likely pathogenic variants of CHD2 (NM_001271.3) were detected, which were predicted to cause their epileptic syndromes." (PMID 35627293, 2022). "Variants in CHD2, CACNA1A, SCN2A, SCN9A, and other genes identified in our cohort have been previously linked to epileptic syndromes." (PMID 41302954, 2025). "For other epilepsy syndromes, CHD2 variation over-representation in the photosensitive GGE or the mixed cohort of photosensitive focal epilepsies failed to meet the corrected threshold for significance." (PMID 25783594, 2015). "Although in some epilepsy syndromes, a ketogenic diet could have vital benefits, a total of four patients with CHD2 variants were treated with the ketogenic diet, which did not produce significant effects." (PMID 35222528, 2022).
schizophrenia (4 papers, 2018 to 2025). A major psychotic disorder characterized by abnormalities in the perception or expression of reality. "We report for the first time a case of schizophrenia in a child with a pathogenic mutation of the chromodomain helicase DNA binding protein 2 (CHD2) gene." (PMID 31914951, 2020). "We describe here for the first time a case of childhood onset schizophrenia eventually linked to the presence of a pathogenic variant of CHD2, which encodes a chromodomain protein involved in neurogenesis, chromatin remodeling and gene expression." (PMID 31914951, 2020). "Chromodomain helicase DNA binding protein 2 (CHD2) gene is involved in neurogenesis, chromatin remodeling, and gene expression, and detrimental mutation in CHD2 has been found relevant to the onset of schizophrenia in children." (PMID 35832186, 2022). "In brief, genetic variants at CHD2 were related to use of sun/UV protection, resting heart rate, free thyroxine levels, educational attainment, measures of body composition, uric acid levels, processed meat intake, pork intake, napping during the day, (standing) height, and schizophrenia." (PMID 41136745, 2025). "However, the precise roles of CHD2 in L1 retrotransposition is yet to be established, which needs further investigation to delineate the mechanism for the treatment of schizophrenia." (PMID 35832186, 2022).
scoliosis (4 papers, 2014 to 2022). A congenital or acquired spinal deformity characterized by lateral curvature of the spine. "One group reported that Chd2+/− mice develop scoliosis, and another revealed that these mice exhibit a shorter lifespan, susceptibility to lymphomas and increased extramedullary hematopoiesis." (PMID 36032672, 2022).
chronic lymphocytic leukaemia (3 papers, 2020 to 2024). "Consistently, CHD2 mutation is one of the most frequently reported genetic alterations in chronic lymphocytic leukaemia (CLL), indicating an additional role in lymphoid development." (PMID 31900031, 2020). "In addition, CHD2 mutation was frequently reported in chronic lymphocytic leukaemia and CHD2 was identified essential for myeloid differentiation." (PMID 38225273, 2024).
developmental and epileptic encephalopathy 94 (3 papers, 2014 to 2024). Developmental and epileptic encephalopathy-94 (DEE94) is a severe form of epilepsy characterized by onset of multiple seizure types in the first few years of life and associated with poor prognosis. "In another report, an exome sequencing screen carried out for de novo mutations in patients with infantile spasms and Lennox-Gastaut syndrome revealed one patient with a CHD2 missense mutation." (PMID 24834135, 2014).
Jeavons syndrome (3 papers, 2018 to 2025).
meningioma (3 papers, 2021 to 2024). A generally slow growing tumor attached to the dura mater. "Then, they repressed two key genes involved in meningioma proliferation (CHD2 and PTPRZ1) by transducing cells with lentiviruses harboring the single guide RNA (sgRNA) targeting the genes." (PMID 33800815, 2021). "Novel somatic driver events identified in these meningiomas were chromatin remodeling and mutations in epigenetic regulators lysine demethylase 6A (KDM6A), chromodomain helicase DNA binding protein 2 (CHD2), and tumor suppressor phosphatase and tensin homolog (PTEN)." (PMID 39726707, 2024). "This CRISPR-induced repression attenuated tumor cell proliferation and was valuable in defining the potential role of chromodomain helicase DNA binding protein 2 (CHD2) and Protein Tyrosine Phosphatase Receptor Type Z1 (PTPRZ1) as novel targets for molecular therapy to treat meningioma patients." (PMID 33800815, 2021).
myoclonic seizure (3 papers, 2020 to 2022). "Most patients with CHD2 variants presented multiple seizure types, especially generalized tonic-clonic seizure (GTCS) (32/59) and myoclonic seizure (MS) (28/59)." (PMID 35627293, 2022). "Among them, myoclonic seizures and generalized tonic-clonic seizures are the main seizure types in all patients hosting CHD2 single-nucleotide or indel variants (non-CNVs)." (PMID 35222528, 2022). "In the CHD2 non-CNVs patients, both the myoclonic seizures (MS, 27.3%, 24/88) and generalized tonic-clonic seizures (GTCS, 19.3%, 17/88) were the top two types of the first seizures, which presented the difference than average value (5.87 people/seizure types)." (PMID 35222528, 2022). "Interestingly, the ages of seizure onset of patients who were seizures control and carried CHD2 non-CNVs were from 1 to 12 years, and generalized tonic-clonic seizures (GTCS, 61.1%, 11/18) and myoclonic seizures (MS, 38.9%, 7/18) were the top two seizure types." (PMID 35222528, 2022).
absence seizures (2 papers, 2015 to 2022). "In general, MS, GTCS, AtS, febrile seizures (FS), absence seizures (AbS), FoS, atypical absence seizures (aAS), and eyelid myoclonia with absence (EMA) were the main seizure types in CHD2 non-CNVs." (PMID 35222528, 2022).
Cognitive decline (2 papers, 2021 to 2025). "CHD2 has previously been reported to interact with repressor element 1-silencing transcription factor (REST), which plays an important role in cognitive decline associated with AD34." (PMID 34011927, 2021).
lung carcinoma (2 papers, 2025). "Herein, we developed the first multiplexed mouse model to study the impact of TBX2 subfamily loss, alongside associated signaling genes (Egr1, Chd2, Tnfaip3a, and Atf3) in Ras-driven lung cancer." (PMID 41705258, 2025).
microcephaly (2 papers, 2022 to 2023). A congenital or acquired developmental disorder in which the circumference of the head is smaller than normal for the person's age and sex. "For example, reduced expression of genes that promote neural progenitor proliferation under CHD2 deficient conditions could contribute to the microcephaly seen in ~ 20% of patients with CHD2 mutations." (PMID 36115870, 2022).